HGF (hepatocyte growth factor)
Diseases named in the same sentence as HGF in open-access papers (continued):
Sharing a sentence is not in itself a finding about the gene and the disease.
breast carcinoma (continued). "Consistently, our data revealed that HGF protein and mRNA levels in fibroblasts derived from the breast cancer patients were positively correlated with their abilities to enhance breast tumorigenesis." (PMID 21249190, 2011). "Herein we demonstrate that Brk mediates HGF-induced cell migration downstream of Met receptors in both breast cancer cells and keratinocytes." (PMID 20687930, 2010). "Breast cancers frequently exhibit dysregulation of HGF and Met signaling, ultimately resulting in increased tumor growth and invasion." (PMID 20687930, 2010). "It is evident from the present study that HGF markedly induced the invasiveness of breast cancer cells." (PMID 29147173, 2010). "Taken together, these results demonstrate a requirement for ERK5 in HGF-induced breast cancer cell migration." (PMID 20687930, 2010). "c-Met and HGF/SF participate in all stages of malignant progression and represent promising drug targets in a variety of cancer types, including breast cancer." (PMID 19796390, 2009). "The ETS1 overexpression promotes malignancy through HGF/Met-mediated motility, which allows breast cancer cells to bypass the requirement of promigratory signals supplied by the environment (such as fibronectin) for invading." (PMID 18941460, 2008). "The potential therapeutic use of TSA should take into account the variable aggressiveness of breast carcinoma cells and microenvironment signals such as HGF at the secondary growth site of the tumour." (PMID 18941460, 2008). "Overexpression of HGF and/or c-Met has been reported in various human cancers, including NSCLCs and breast cancers." (PMID 15083185, 2004). "Given the cooperative effects between CCL2 and HGF on breast cancer cells, we hypothesized that targeting CCR2 or MET alone would inhibit DCIS progression more effectively than inhibiting CCR2 or MET alone." (PMID 40736024, 2025). "CCL2/HGF-mediated cellular phenotypes were associated with increased AMPK, p42/44MAPK, AKT and PKC signaling, indicating cooperative roles for CCL2 and HGF signaling in breast cancer for both cell lines." (PMID 40736024, 2025). "Understanding the specific mechanisms that regulate CCL2 and HGF expression are regulated in breast cancer may enable us to predict when CCR2 and MET signaling may be altered during breast cancer progression." (PMID 40736024, 2025). "CCL2/CCR2 and HGF/MET signaling pathways are upregulated in breast cancers." (PMID 40736024, 2025). "Similarly, MET overexpression is observed in many other cancers, including breast cancer (BC), where serum HGF levels increase with BC and are higher in patients with mBC." (PMID 40723207, 2025). "Thus, a positive correlation between STMN1, MET, and HGF expression and metastasis, responsiveness to taxane, and overall survival in prostate and breast cancer patients is based on total STMN1 expression within these tumors." (PMID 40723207, 2025). "The association of hepatocyte growth factor (HGF) with breast cancer was stronger in Estrogen Receptor (ER)-negative patients, while CASP8, CXCL11, MMP7, and C–C motif chemokine 4 (CCL4) were associated with ER-positive breast cancer." (PMID 40665092, 2025). "CCL2/CCR2 and HGF/MET cooperate to enhance breast cancer progression and metabolic reprogramming." (PMID 40736024, 2025). "In summary, these findings on CCL2/CCR2 and HGF/MET signaling in early-stage breast cancer could be used to tailor treatments for patients with DCIS." (PMID 40736024, 2025). "However, to the best of our knowledge, there are currently no published data demonstrating the effects of TAS-115 on c-MET/HGF interactions in breast cancer and metastasis." (PMID 41289612, 2025). "HGF is a key pathway in the occurrence of breast cancer and has racial expression differences." (PMID 40860340, 2025). "Recent reports revealed that the prognostic impact of HGF in breast cancer could be determined by the race of patients." (PMID 39302921, 2024).
breast carcinoma (continued). "Notably, heightened expression of HGF and c-Met correlated with poorer recurrence-free survival among breast cancer patients who underwent radiation therapy." (PMID 39408826, 2024). "In this study, HGF was the least expressed in breast cancer tissues." (PMID 39302921, 2024). "The activation of astrocytes contributes to the progression of brain metastasis in the brain metastatic microenvironment by promoting the proliferation and invasion of brain metastatic breast cancer cells through the secretion of neurotrophic factors such as hepatocyte growth factor (HGF)." (PMID 38111675, 2023). "However, miR-200a-5p has the opposite effect in breast cancers as suppresses cell proliferation by regulating the expression of hepatocyte growth factor (MET) and epidermal growth factor receptor (EGFR)." (PMID 36991314, 2023). "In breast cancer (BC), RNAseq revealed increased expression of transcripts encoding immune regulatory receptors (CD200R1), pro-apoptotic molecules (TNFSF10), and pro-angiogenic factors (HGF and ANGPT1) in BC patients compared to healthy donors." (PMID 36733385, 2022). "We demonstrated that CDCP1 promoted HGF-induced migration and invasion of breast cancer cells." (PMID 35085554, 2022). "In addition, weight loss significantly reversed the HFD-induced effects on latency and the activation of HGF/cMET signaling in normal mammary tissue and cMET in normal mammary and breast cancer tissue." (PMID 35563777, 2022). "Moreover, the inhibition of α9, α2β1, and α3β1 integrins with relevant specific blocking antibodies significantly reduced HGF-induced migration of lymphocytic endothelial cells and breast carcinoma cells." (PMID 36330337, 2022). "Studies with breast cancer, bladder cancer and hepatoma cells indicated that over-expression of hepatocyte growth factor (HGF) may down-regulate cadherin-mediated cell-cell adhesion with consequent migration and invasion into mesenchymal cells." (PMID 35887822, 2022). "Thus, increased expression of HGF promoted c-Met-induced cell proliferation and subsequent progression of breast cancer." (PMID 36010901, 2022). "Studies have also shown that ADSCs in the breast tissue can promote invasion of breast cancer cells via a VEGF-A-dependent manner, and ADSCs may favor breast cancer recurrence via HGF/c-Met signaling." (PMID 34362454, 2021). "The effect of the HGF/MET signaling pathway on breast cancer cells requires the presence of SIPA1." (PMID 33917539, 2021). "Furthermore, Crk knockdown inhibited hepatocyte growth factor (HGF)-induced migration of breast cancer cells." (PMID 33801580, 2021). "Moreover, it has been shown that 3T3-L1 adipocytes stimulated the growth of SP1 cells, which represent murine mammary carcinomas, by secreting hepatocyte growth factor (HGF)." (PMID 34822423, 2021). "Colocalisation analysis suggested that the association of HGF with oestrogen receptor‐negative breast cancer was unlikely to reflect a causal association." (PMID 32134113, 2020). "Overexpression of miR-335 has been shown to suppress HGF-induced phosphorylation of c-Met, which could subsequently inhibit the HGF role of prompting breast cancer cell migration in a c-Met-dependent manner by targeting c-Met." (PMID 32083078, 2020). "Preoperative serum HGF is a tumor peripheral biomarker of breast cancer that could predict the prognosis of breast cancer." (PMID 32607415, 2020). "Apart from direct cell-to-cell contact, CAF-secreted hepatocyte growth factor (HGF) binds to c-MET receptor on breast cancer cells, leading to alternative activation of the PI3K/AKT signalling pathway and attenuation of HER2 inhibitor sensitivity in basal-like breast cancer cells." (PMID 32595946, 2020). "Moreover, overexpression of CXCR4, HGF, and c-MET in primary breast cancer is associated with worse patient outcomes in females." (PMID 32188473, 2020).
breast carcinoma (continued). "Therefore, although differences between male and female breast cancer become apparent, the crosstalk among predominant biologic pathways and their function in males is not well understood, including that of the HGF/c-MET signaling." (PMID 32188473, 2020). "Recent studies showed that NCTD could overcome doxorubincin resistance in breast cancer cells and Hepatocyte growth factor (HGF) induced resistance to epidermal growth factor receptor tyrosine kinase inhibitors (EGFR-TKI) in lung cancer cells." (PMID 31120927, 2019). "It was also reported that upregulation of heparanase in myeloma and breast cancer cells is associated with increased release of Syndecan-1, Vascular Endothelial Growth Factor (VEGF), and Hepatocyte Growth Factor (HGF) in EVs, leading to increased endothelial invasion through the ECM." (PMID 30925923, 2019). "The addition of BFE alone (10 μg/ml) did not reveal any obvious differences to the untreated cells, however the additional of BFE in combination with HGF revealed a dramatic reduction in the migration of the breast cancer cells after 6 h when compared to the HGF treatment group." (PMID 30314527, 2018). "IKKβ stimulates the CK1α-mediated degradation of Rap guanine exchange factor 2 (RAPGEF2) via phosphorylation at Ser1244 and Ser1248 in response to hepatocyte growth factor (HGF), and may promote the dissemination and metastasis of human breast cancer cells." (PMID 29793495, 2018). "The pro-metastatic influence of HGF on these cells was further demonstrated, as the breast cancer cells that were cultured in the presence of HGF showed a dramatic increase in the number of cells invaded (BT549: 23.5 ± 6.1, p = 0.001; MDA-MB-231: 65.8 ± 26.2, p = 0.005)." (PMID 30314527, 2018). "In addition, WWOX was shown to play an important role in hepatocyte growth factor (HGF) mediated mesenchymal to epithelial transition (MET) in breast cancer bone metastasis." (PMID 30619734, 2018). "However, HGF can also be produced by several tumor cell types and is detected in the renal cell, colorectal and breast carcinomas, glioma, multiple myeloma and synovial, osteo- and fibrosarcoma." (PMID 30352967, 2018). "Hence, we define TGFβ1 as a regulator of MET expression in breast cancer by upregulating C‐ets‐1 and downregulating miR‐128‐3p expression, which results in cell migration, invasion, and metastasis in a HGF‐dependent manner." (PMID 30004628, 2018). "In addition to the 3D growth behavior, we also determined the effects of scavenging ROS with MnTE on HGF-mediated invasion of breast cancer cells." (PMID 29296173, 2017). "The antioxidant, MnTE inhibited HGF-mediated growth of breast cancer cells by 76% (P = 0.017)." (PMID 29296173, 2017). "The association of HGF and breast cancer progression has primarily been shown in triple-negative breast cancers; our data are mainly based on ER+ breast cancer, whether HGF is increased in ER− human breast cancer remains to be elucidated." (PMID 29387062, 2017). "We also measured three key pro-tumorigenic growth and angiogenic factors associated with inflammation, TGF-α, FGF-19, and HGF, and showed that both TGF-α and FGF-19 exhibited increased levels in both breast cancer and dense breast tissue compared with their normal tissue counterparts." (PMID 29387062, 2017). "Interestingly, the concentrations of HVS required to induce 50% inhibition of cancer cell growth were significantly greater when breast cancer cells maintained in HGF-free media as compared to those maintained in media supplied with HGF as a mitogen." (PMID 27086914, 2016). "In this case, adipose progenitor cells infiltrating into the scaffold may stimulate breast cancer recurrence via HGF/c-Met signalling." (PMID 27301425, 2016). "However, the IC50 values for HVS in HGF-free media were > 40 μM in the four breast cancer cell lines." (PMID 27086914, 2016).
breast carcinoma (continued). "The clinical importance of HGF and its receptor c-Met has been further demonstrated in recent studies, showing that the levels of c-Met in mammary cancer tissues and levels of circulating HGF in patients with mammary cancer are associated with a lower survival and development of distant metastasis." (PMID 26919096, 2016). "In addition to decreased TGF-β expression, breast cancer stroma also show increased expression of HGF, a growth factor that acts on breast cancer cells to promote tumor growth and invasion." (PMID 26252654, 2015). "ADSCs increase HGF production in presence of c-MET positive primary breast cancer cells, which in turn increase their HGF production; this observation confirms that the stroma creates a microenvironment where cancer cells are continuously stimulated to proliferate." (PMID 28536400, 2015). "Moreover, inhibition of Abl kinases with either STI571 or GNF2 decreased HGF-induced MDA-MB-231 breast cancer cell migration in a wound healing assay." (PMID 25946048, 2015). "The aim of this review is to explore the roles of HGF/c-Met signalling in breast development, different in vitro and in vivo models of breast cancer, and the various mechanisms of aberrant c-Met signalling identified in breast cancer tissue." (PMID 25887320, 2015). "Since their discovery, the literature regarding c-Met and HGF in the breast has grown rapidly, and there is now a need to consolidate the findings from these studies to better understand the relevance of anti-c-Met therapy in breast cancer." (PMID 25887320, 2015). "Additionally, p66ShcA overexpression promotes EMT in ErbB2-driven breast cancer cells, through up-regulated activation of the c-Met receptor by its ligand hepatocyte growth factor (HGF)." (PMID 26680585, 2015). "While TGF-β and HGF are both co-expressed in the tumor, our studies indicate that low TGF-β concentrations and high HGF concentrations in the local breast cancer stroma may result in increased CXCL1 expression." (PMID 26252654, 2015). "In addition to autocrine factors (hepatocyte growth factor or fibroblast growth factor 2), H19 expression is also regulated by estrogen signaling in ERα+ breast cancer cells." (PMID 25944846, 2015). "HGF promotes resistance to drugs targeting HER2 in breast cancer and BRAF in melanoma cell lines." (PMID 25946048, 2015). "Additionally, HGF overexpressing mammary tumors led to increased phosphorylation of the c-Met receptor." (PMID 25938541, 2015). "Here, we report our observations of the effect of knocking down SOCS7 gene on the behaviour of breast cancer cells both in vitro and in vivo and to elucidate whether this involves HGF/C-MET pathway using the PLCγ-1 blocker U73122." (PMID 25162020, 2014). "Interestingly, concentrations of (-)-oleocanthal required to induce 50% inhibition of cancer cell growth were greater for breast cancer cells maintained in HGF-free media as compared to those maintained in media supplied with HGF." (PMID 24849787, 2014). "The HGF/c-Met axis is one such pathway linked to both obesity and breast cancer risk that previously had not been investigated in tandem." (PMID 25072025, 2014). "Moreover, breast cancer patients with a high HGF concentration had a significantly poor prognosis when compared to those with a low HGF concentration." (PMID 25075970, 2014). "Actually, HGF/c-Met was reported to be required for mammalian gland development, and was found deregulated in several human cancers, accounting for increased invasiveness and tumorigenicity predicting poor outcome in breast cancer patients." (PMID 24327602, 2014).
breast carcinoma (continued). "Therefore, HGF level was found to be the most important independent factor in predicting the prognosis of breast cancer." (PMID 25075970, 2014). "In their gene candidate studies, Finegold and coworkers found HGF and cMET mutations in single subjects with primary lymphedema, lymphangiectasia, and breast cancer-related lymphedema (BCRL) subjects that were not polymorphic in control populations." (PMID 25383712, 2014). "In this study we hypothesised a regulatory role for SOCS7 in HGF/C-MET signalling in breast cancer based on its multiple interactions with intermediate molecules downstream of the C-MET receptor." (PMID 25162020, 2014). "Interestingly, co-culture of normal mammary fibroblasts with breast cancer cells can ‘educate’ the fibroblasts to secrete HGF and increase their tumor-promoting activities." (PMID 25011545, 2014). "Moreover, it was further confirmed beta-catenin involvement to mediate HGF/c-Met signaling, in breast cancer cells and ASCs crosstalk." (PMID 24327602, 2014). "To focus on cytokines and growth factors specifically produced by ASCs (EGF, FGF, HGF, SDF, IL6, IL8, IL10) or epithelial breast cancer cells (EGF, FGF, HGF) known to be relevant in tumorigenesis, we carried out Q-PCR analyses both on ASCs or primary breast cancer cells, before and after co-culture." (PMID 24327602, 2014). "Indeed, we found ASCs increased HGF production in presence of c-Met positive primary breast cancer cells, which increased their own HGF production in turns." (PMID 24327602, 2014). "Their studies showed that activation of EGFR and HGF might contribute to drug resistance of breast cancer through the downregulation of phosphosites such as Thr654 and Thr669 of EGFR." (PMID 25478227, 2014). "Moreover our findings reveal an additional role of HGF/c-Met signaling in co-cultured breast cancer cells: the regulation of CICs subpopulation via beta-catenin regulation." (PMID 24327602, 2014). "Similarly, (-)-oleocanthal blocked HGF-induced invasion of the highly invasive MDA-MB-231 breast cancer cells." (PMID 24849787, 2014). "Studies using + SA mammary tumor cells maintained in serum-free defined media containing HGF as a mitogen show that HGF induces a dose-responsive increase in growth and corresponding increase in Met autophosphorylation, whereas combined treatment with γ-tocotrienol blocks these effects." (PMID 26932375, 2014). "In addition to its predictive expression in human mammary tumours, HGF is a potent mammary tumour inducer in mice, as targeted expression of HGF in mouse mammary epithelium was found to lead to metastatic adenocarcinomas." (PMID 25162020, 2014). "In a study that evaluated hepatocyte growth factor (HGF) and the high affinity hepatocyte growth factor receptor (MET) in 59 women with breast cancer related LE, mutations leading to truncation or missense changes in evolutionarily conserved residues of HGF and MET were identified." (PMID 23613720, 2013). "Recently, our research group reported that the extract product of Ephedra herb (“Ephedra herb extract”) inhibits the hepatocyte growth factor (HGF)-induced motility of human breast cancer MDA-MB-231 cells through the suppression of c-Met tyrosine phosphorylation." (PMID 23666001, 2013). "Adding exogenous HGF to these breast cancer cell lines decreased sensitivity to EGFR TKIs." (PMID 22788954, 2012). "In addition, Zhang and colleagues used a novel mouse model to demonstrate that HGF expression can promote tumor growth of EGFR-expressing breast cancers." (PMID 22788954, 2012). "However, the mechanism of the CXCR4 expression modulated by c-Met-HGF axis to enhance the metastatic behavior of breast cancer cells is still unclear." (PMID 22242160, 2012). "Recent evidence shows that EGFR may play a significant role in some HGF/Met mediated biological responses of mammary tumor and epithelial cells." (PMID 23028720, 2012).